INS (insulin)
Diseases named in the same sentence as INS in open-access papers (continued):
Sharing a sentence is not in itself a finding about the gene and the disease.
type 2 diabetes (continued). "PFASs pose a risk factor for Hepatocellular Carcinoma (HCC) by disrupting insulin and glucose regulation, characteristics often seen in type 2 diabetes." (PMID 40066031, 2025). "They contribute to the regulation of insulin sensitivity and glucose metabolism, potentially influencing the occurrence of some metabolic disorders such as type 2 diabetes or obesity." (PMID 40650200, 2025). "IR is a key pathogenic component in a variety of metabolic diseases, including type 2 diabetes, and is defined as a reduced responsiveness of insulin-targeted tissues to physiological insulin levels." (PMID 40625623, 2025). "Type 2 diabetes mellitus (T2DM) is a chronic metabolic disorder characterized by insulin resistance and impaired insulin secretion, leading to hyperglycemia and an increased risk of microvascular and macrovascular complications." (PMID 40385819, 2025). "This reduction suggests that ginger improves insulin sensitivity, making it an effective adjuvant therapy for individuals with type 2 diabetes and metabolic syndrome." (PMID 40565030, 2025). "Tnfα serum levels are increased in patients with obesity or type 2 diabetes, leading to reduced insulin sensitivity and adiponectin secretion." (PMID 40498013, 2025). "Numerous in vitro and in vivo studies link the reduction of oxidative stress through anthocyanins to increased insulin production in pancreatic β-cells of individuals with type-2 diabetes." (PMID 39136514, 2025). "For example, a DT-based program for patients with type 2 diabetes helped all 12 insulin-dependent patients who attended the program to stop insulin injections and helped 38 out of 56 to stop taking metformin." (PMID 39778199, 2025). "Defects in insulin secretion or action can result in abnormal glucose and lipid metabolism, a major complication of type 2 diabetes." (PMID 41245272, 2025). "It is well established that obesity is associated with decreased insulin clearance in adults and in children; however, the impact of dysglycemia (IGT and/or type 2 diabetes) remains somewhat controversial." (PMID 40470991, 2025). "In pathological conditions like obesity and type 2 diabetes, skeletal muscle insulin sensitivity is blunted, reducing its capacity to incorporate glucose and contributing to hyperglycemia." (PMID 40332335, 2025). "The pancreas is unable to produce enough insulin in people with type 2 diabetes, and there is evidence that this impairment is exacerbated by beta cell loss." (PMID 39940428, 2025). "This study aimed to evaluate the long-term cost-effectiveness of IDegLira versus GLP-1RA added to basal insulin regimen (combined regimen) for patients with type 2 diabetes in China." (PMID 39913436, 2025). "In type 2 diabetes, the function of islet beta cells to secrete insulin is impaired, while the responsiveness of the target organ to insulin is reduced, leading to hyperglycemia." (PMID 40650120, 2025). "Type-2 diabetes develops when the compensatory insulin synthesis cannot keep up with the insulin demand of the insulin-resistant target cells, leading to hyperglycemia." (PMID 41514592, 2025). "The major subtypes of diabetes are type 1 diabetes and type 2 diabetes, which classically result from defective insulin secretion (type 1 diabetes) and/or action (type 2 diabetes)." (PMID 40142691, 2025). "Studies have shown that CGM use helps lower A1c among people with type 2 diabetes using intensive insulin therapy (i.e., multiple daily injections or insulin pumps) or basal insulin therapy." (PMID 40851538, 2025). "Individuals with reduced insulin sensitivity or those who later developed type 2 diabetes had significantly higher plasma valine and leucine levels." (PMID 41282284, 2025). "The numbers of insulin-producing β cells in the pancreas are reduced in people with type 1 or type 2 diabetes, prompting efforts to replace these missing or lost β cells through transplant or regenerative medicine approaches." (PMID 41031887, 2025).
type 2 diabetes (continued). "We developed an innovative bilingual toolkit comprising a personalized action plan and educational videos to encourage insulin dose self-titration by adults living with type 2 diabetes." (PMID 41313169, 2025). "Type 2 diabetes (T2D) is the most prevalent form, resulting from insulin resistance where cells fail to respond effectively to insulin, leading to impaired glucose regulation." (PMID 41305240, 2025). "Despite similar clinical manifestations, DM is classified into two primary types: Type 1 diabetes, marked by insufficient insulin production, and Type 2 diabetes, characterized by insulin resistance." (PMID 39861189, 2025). "Traditionally, type 1 and type 2 diabetes are managed by controlling blood glucose levels through insulin pumps or injections of insulin or GLP-1." (PMID 39399837, 2025). "This is especially necessary for those with type 1 diabetes who must use insulin therapy as their mainstay and type 2 diabetes who cannot control or tolerate oral medications." (PMID 40242444, 2025). "IF has gained attention for its potential therapeutic applications in improving insulin function and glucose homeostasis in both healthy individuals and those with type 2 diabetes." (PMID 40777199, 2025). "Type 2 diabetes accounts for the vast majority (>90%) of these cases, primarily driven by insulin resistance and dysfunction of β-cells." (PMID 41301787, 2025). "Once‐daily basal insulin is widely used in the management of type 2 diabetes, but poor adherence to daily injections often impairs glycaemic control." (PMID 41152194, 2025). "mTOR regulates insulin signaling via IRS1 in metabolic tissues and is implicated in diseases like type 2 diabetes, obesity, and cancer." (PMID 40243885, 2025). "Type 2 diabetes is more likely to develop because the body’s cells are less sensitive to insulin over time, necessitating higher hormone levels to regulate blood glucose." (PMID 39940428, 2025). "Insulin signaling plays an important role in the development of type 2 diabetes, and the insulin receptor has been indicated as a substrate of BACE1." (PMID 40507910, 2025). "This research clearly indicates that the interaction between neuronal glucose-sensing cells and islet α and β cells is essential for maintaining proper insulin and glucagon levels in the blood, a process that is impaired in type 2 diabetes." (PMID 40940782, 2025). "This section discusses the role of NAD+ in energy metabolism, its association with Type 2 diabetes, and how NAD+‐dependent enzymes—such as sirtuins—impact insulin sensitivity and metabolic function." (PMID 40289598, 2025). "On simple group comparisons, patients treated with insulin (type 1 and insulin-treated type 2) had PDR more often than those with type 2 diabetes managed only with oral drugs." (PMID 41156463, 2025). "Despite β‐cell failure in youth with dysglycemia (i.e., impaired glucose tolerance [IGT] and type 2 diabetes), fasting insulin (FI) concentrations are elevated." (PMID 40470991, 2025). "Icodec is a basal insulin analogue studied in six phase 3a randomised trials as part of the ONWARDS clinical trial programme in individuals with type 2 diabetes or type 1 diabetes." (PMID 39820580, 2025). "The peroxisome proliferator-activated receptor gamma (PPARG) gene, located on the 3p25 chromosome in type 2 diabetes, controls lipid metabolism while simultaneously affecting insulin sensitivity." (PMID 40225541, 2025). "This study suggests that resistance training is beneficial for improving insulin utilization in patients with type 2 diabetes." (PMID 40951419, 2025). "In patients with type 2 diabetes, about 20 U of insulin is typically injected per day, which is equivalent to about 120 μM." (PMID 40723866, 2025). "The number of p16INK4A+ and p21cip1+ (cyclin-dependent kinase inhibitors 2A and 1A, respectively) beta cells (with colocalised insulin staining), indicative of senescence, was significantly increased in both older donors and donors with type 2 diabetes." (PMID 40133488, 2025).
type 2 diabetes (continued). "Pharmacotherapy in type 2 diabetes, such as sulphonylureas, glitazones, and insulin, contributes to undesirable consequences like weight gain or the exacerbation of the severity of existing OSAS, thus increasing cardiovascular risks." (PMID 40508878, 2025). "In type II diabetes patients, aerobic training can reduce glycosylated hemoglobin (HbA1c), triglyceride, and insulin resistance." (PMID 40362436, 2025). "We report an 80-year-old man with type 2 diabetes who presented with life-threatening hypoglycemia (36 mg/dL) and coma, requiring high-dose insulin (74 units/day)." (PMID 41696731, 2025). "Maintaining optimal postprandial blood glucose and insulin levels is critical for preventing type II diabetes." (PMID 40944237, 2025). "This mini-review summarizes the recent findings from clinical trials evaluating once-weekly insulin therapies in both type 1 and type 2 diabetes." (PMID 40937414, 2025). "Intranasal insulin has shown promise in improving cognition in early Alzheimer's disease and type 2 diabetes, supporting the concept that restoring insulin sensitivity can mitigate neurodegeneration." (PMID 40536952, 2025). "As a result, more and more people suffer from illnesses that develop because of the disturbed metabolic function of insulin, including type 2 diabetes, nonalcoholic fatty liver disease and polycystic ovarian syndrome." (PMID 41009549, 2025). "Treatments: 1) Type 2 diabetes: mixed protamine zinc recombinant human insulin lispro injection (50 R), 26 IU, subcutaneous injection, twice a day; acarbose capsule, two capsules, oral before food." (PMID 40831950, 2025). "Pioglitazone belongs to the insulin-sensitizing agents thiazolidinediones (TDZs) and is an approved drug for type 2 diabetes." (PMID 40867509, 2025). "In type 2 diabetes (T2DM), prolonged hyperglycemia causes both functional decline of insulin-producing β-cells and systemic insulin resistance." (PMID 40943666, 2025). "Type 2 diabetes is a complex metabolic disorder with diverse characteristics, marked by a reduction in insulin secretion and/or its activity, resulting in elevated blood glucose levels (hyperglycemia)." (PMID 40647906, 2025). "Type 2 diabetes is characterized by pancreatic beta-cell dysfunction and reduced insulin sensitivity." (PMID 41394924, 2025). "GLP-1 is a pivotal incretin hormone that enhances insulin secretion, making it a key target in the management of type 2 diabetes and obesity." (PMID 40806100, 2025). "Current therapeutic approaches for type 2 diabetes aim to improve glycemic control, enhance insulin sensitivity, and prevent long-term complications." (PMID 41304970, 2025). "Research has also shown that SGLT-2 inhibitors and GLP-1 receptor agonists reduce the dosages of insulin needed among people with type 2 diabetes." (PMID 40245017, 2025). "Numerous studies have demonstrated that NAFLD prevalence is markedly higher in insulin-resistant states, including obesity, type 2 diabetes, dyslipidemia, and metabolic syndrome." (PMID 40640543, 2025). "Troglitazone, an insulin-sensitizing agent, was initially used to treat Type II diabetes by activating PPAR-γ receptors, which regulate genes involved in glucose and fatty acid metabolism." (PMID 40334012, 2025). "The calcium signaling pathway regulates liver functions like bile secretion and glucose metabolism, and dysregulation of the insulin secretion pathway is associated with NAFLD and type 2 diabetes." (PMID 40153413, 2025). "Supervised low-volume HIIT significantly improved pancreatic β-cell function, which is adjusted for insulin sensitivity and can predict the development of type 2 diabetes." (PMID 41375630, 2025). "The diminished insulin responsiveness ultimately can disturb whole‐body glucose homeostasis, contributing to metabolic dysregulation and increased transition to type 2 diabetes." (PMID 40329491, 2025).
type 2 diabetes (continued). "Type 2 diabetes mellitus (T2DM) is a condition characterized by high blood glucose levels due to inadequate or ineffective utilization of insulin by the body." (PMID 40509460, 2025). "This is somewhat surprising given the established effects of acute exercise in potentiating insulin action on amino acid uptake and increasing insulin sensitivity in healthy individuals, as well as in individuals with type 2 diabetes." (PMID 40404819, 2025). "In preclinical models, XN has exhibited the ability to improve insulin sensitivity, regulate blood glucose levels, and ameliorate lipid profiles, positioning it as a potential therapeutic for type 2 diabetes and metabolic syndrome." (PMID 39942798, 2025). "In general, resistance training enhances insulin sensitivity and improves fasting glucose levels in individuals diagnosed with type 2 diabetes." (PMID 40951419, 2025). "Troglitazone is a PPAR-γ agonist that was used to enhance insulin sensitivity in patients with type 2 diabetes but was withdrawn from the market in 2000 by the FDA due to numerous cases of liver failure from DILI." (PMID 41444459, 2025). "Carnosine supplementation has been shown to increase serum insulin concentration in rodent models of obesity and type-2 diabetes but also in human studies in obese or type-2 diabetic individuals." (PMID 40002779, 2025). "In 344 insulin-experienced veterans with stable type 2 diabetes, ~10% of all participant-documented hypoglycaemic episodes were attributed to exercise." (PMID 40186685, 2025). "Medical situations in which insulin therapy is generally used and preferred over other glucose‐lowering medications in people with type 2 diabetes." (PMID 40035222, 2025). "Among these signals was the IRS1 region, again providing evidence of the relevance of insulin resistance pathways to the development of type 2 diabetes and CAD." (PMID 40088285, 2025). "Prior studies have demonstrated that caffeine intake is associated with increased postprandial plasma glucose and insulin in individuals with type 2 diabetes and with reduced insulin sensitivity in healthy adults." (PMID 41416067, 2025). "Dipeptidyl peptidase IV (DPP-IV) inhibitory peptides have emerged as promising functional ingredients for managing type 2 diabetes due to their ability to enhance insulin secretion and improve glycemic control." (PMID 40361562, 2025). "Type 2 diabetes mellitus (T2D) is a chronic metabolic disorder characterized by persistent hyperglycemia, resulting from a combination of insulin resistance and impaired insulin secretion." (PMID 40509445, 2025). "It is well accepted that FFA plays a role in regulating insulin secretion in response to a meal, in the development of type 2 diabetes, and chronic exposure to FFA can result in β-cell dysfunction." (PMID 40671915, 2025). "BACKGROUND references highlight physiological mechanisms like insulin sensitivity and glucose metabolism foundational to type 2 diabetes research." (PMID 40552083, 2025). "Given that type 1 diabetes is more difficult to manage than type 2 diabetes, there is a need to explore adjunctive therapies to insulin that can improve glycemic control and reduce insulin requirements." (PMID 41026724, 2025). "The development of type-2 diabetes via hyperinsulinemia is explained by a proposed interplay among insulin, GH, and IGF-I." (PMID 41514592, 2025). "Compared to previous studies on antidiabetic treatments in both PTDM patients and the broader type 2 diabetes population, our findings largely align with established evidence regarding the efficacy of insulin, SGLT2i, and DPP-4 inhibitors." (PMID 40995094, 2025). "Type 2 diabetes mellitus (T2DM) develops as a result of the inability to use the insulin hormone effectively or to produce it insufficiently." (PMID 39982630, 2025).
type 2 diabetes (continued). "Sulfonylureas, the oldest class of medications for the treatment of type 2 diabetes, akin to KCl treatment, induce membrane depolarization and insulin secretion by binding to the sulfonylurea receptor subunit on ATP-sensitive potassium channels." (PMID 40355555, 2025). "These molecular alterations converge in type 2 diabetes, where PTM imbalance underlies impaired insulin signaling and metabolic inflexibility." (PMID 41373704, 2025). "This study provides valuable insights into the prevalence and characteristics of anti-insulin antibodies (IAs) in patients with type 1 diabetes (T1D) and type 2 diabetes (T2D) undergoing insulin therapy." (PMID 40004193, 2025). "The core mechanism of type 2 diabetes lies in the dual defect of insulin resistance and β‐cell dysfunction." (PMID 41268707, 2025). "In these monkeys, a 10-fold increase in basal (fasting) plasma insulin levels and a five-fold increase in insulin response to glucose were observed in the earliest stages of type 2 diabetes." (PMID 41009753, 2025). "Levels of ImP are elevated in individuals with type 2 diabetes (T2D), and ImP impairs glucose tolerance and insulin signalling when administered to mice." (PMID 41277458, 2025). "The resulting hyperglycemia stimulates additional insulin release, creating a vicious cycle that can culminate in the development or worsening of type 2 diabetes." (PMID 40136609, 2025). "Imeglimin, developed in Japan, is a novel oral agent for type 2 diabetes that uniquely targets both insulin secretion and mitochondrial health." (PMID 40822946, 2025). "DPP-4i extends the half-life of GLP-1, thereby enhancing insulin production and diminishing glucagon release, which leads to improved glycemic control in individuals with type 2 diabetes mellitus (T2DM)." (PMID 40427515, 2025). "Cord blood glucose, insulin and leptin were increased in infants of type 2 diabetes mothers and increased leptin was positively correlated with maternal leptin and birth weight." (PMID 40045330, 2025). "This approach is particularly significant for modeling chaotic behaviors, such as those in the insulin-glucose system, where accurate representation is crucial for managing conditions like type 1 and type 2 diabetes, hypoglycemia, and hyperinsulinemia." (PMID 41345203, 2025). "Some studies demonstrated beneficial effects of consuming magnesium on improving insulin sensitivity in people with hyperglycemia, type 2 diabetes (T2D), metabolic syndrome and PCOS." (PMID 40005397, 2025). "In the context of metabolic disorders, particularly type 2 diabetes and obesity, 5‐HT has been shown to regulate glucose metabolism, insulin sensitivity, and adipose tissue inflammation." (PMID 40937192, 2025). "Although type 1 myotonic dystrophy is characterized by muscle stiffness and RNA toxicity, and type 2 diabetes is primarily driven by insulin resistance, the two conditions have distinct etiologies." (PMID 41018201, 2025). "The PI3K/Akt signaling axis also plays a major role in insulin-mediated metabolic processes, and Akt inhibition contributes to insulin resistance and the pathogenesis of type II diabetes mellitus." (PMID 40653199, 2025). "Systemic arterial hypertension was highly prevalent (94.54%), whereas diabetes mellitus type II affected 33.60% of patients (4.65% on insulin therapy)." (PMID 41584286, 2025). "- A trial of marine collagen peptides in type 2 diabetic patients found improvements in fasting glucose, HbA1c, insulin, and lipid levels." (PMID 40843204, 2025). "Similar alterations in the islet cell phenotype occur in type 2 diabetes, in which an increase in the proportion of islet cells co-expressing insulin, glucagon and Nkx6.1, and glucagon with Nkx6.1, was found." (PMID 39860066, 2025).